NRP1 (neuropilin 1)
Diseases named in the same sentence as NRP1 in open-access papers (continued):
Sharing a sentence is not in itself a finding about the gene and the disease.
glioma (continued). "Next, to ascertain if GDNF promoted proliferation of C6 glioma cells through NRP1, we performed knockdown of rat NRP1 using the lentivector shRNA transduction of C6 glioma cells." (PMID 29088765, 2017). "Using laser scanning confocal microscopy, we observed that exogenous GDNF recruited NRP1 protein to the C6 glioma cell membrane." (PMID 29088765, 2017). "CCK8 proliferation assay showed that NRP1 RNAi resulted in decreasing proliferation of C6 glioma cells treated with exogenous GDNF compared to C6 cells transduced with CON77 RNAi (P < 0.05)." (PMID 29088765, 2017). "In contrast, genes encoding angiogenic factors (ANGPT1, ANGPT2) and receptors (NRP1, and KDR) were highly expressed in SA-culture-derived glioma cells of 51B." (PMID 29113349, 2017). "We demonstrate here using a syngeneic glioma model that tumors develop more slowly in mice in which Nrp1 has been genetically ablated from their microglia and macrophages." (PMID 26755653, 2016). "Taken together, these findings support the investigation of Nrp1-selective inhibitors as potential therapeutics for gliomas." (PMID 26755653, 2016). "Nrp1 expression was detected by immunofluorescence in Iba1-positive GAMs in glioma biopsies of varying grades." (PMID 26755653, 2016). "Our results demonstrate that Nrp1 signaling in GAMs plays a key role in their interaction with the glioma microenvironment, promoting their polarization to a pro-tumorigenic phenotype and thereby facilitating tumor growth and neovascularization." (PMID 26755653, 2016). "Even though NRP1 acts mainly as a SEMA3A receptor, and NRP2 as a SEMA3F receptor in neurons, NRP2 can compensate for NRP1 as a SEMA3A-receptor during glioma cell migration in vitro and in vomeronasal axon guidance in mouse embryos in vivo." (PMID 26923176, 2016). "Since inhibition of Nrp1-dependent pathways has been reported to affect the growth of glioma-derived tumor cell lines, we investigated the capacity of increasing amounts of EG00229 to suppress growth and migratory behavior of the GL261-eGFP cell line in vitro." (PMID 26755653, 2016). "NRP1 has been reported to be over-expressed in various cancers including breast, prostate, pancreatic, colon, gliomas and its expression has been reported to correlate with poor prognosis." (PMID 26097868, 2015). "An upregulation of Nrp-1 in glioma cells was found to promote tumor growth and angiogenesis in vivo." (PMID 23050142, 2012). "Analyses of human glioma specimens revealed a significant correlation of Nrp-1 expression with glioma progression to high grades." (PMID 23050142, 2012). "Increased expression of NRP1 has also been detected in tumour cells from clinical glioma samples, suggesting a link between NRP1 expression and glioma malignancy." (PMID 18781179, 2008). "Additionally, pharmacological and genetic ablation of NRP1 in macrophages and microglia induced anti-tumorigenic phenotypes in a glioma model, correlating with classical M1 macrophage activation." (PMID 40134439, 2025). "Analysis of glioma tumors from the TCGA French cohort shows increased levels of NRP1 transcripts in GBMs as well as in other types of higher-grade gliomas, such as grade III astrocytomas, oligoastrocytomas, and oligodendromas, compared to non-tumoral-brain-tissue or lower-grade gliomas." (PMID 37894289, 2023). "In addition, mRNA expression levels of NRP1 in glioma specimens positively correlated with those of Sema3A or TGF-βR1, as determined by The Cancer Genome Atlas (TCGA) data analysis." (PMID 37788099, 2023). "Neuropilin-1 (NRP-1) receptors are expressed in various cancers including glioma cells." (PMID 37508353, 2023). "For example, one study demonstrated how engineered EVPs, containing therapeutic siRNA, could target glioma cells by expressing a protein that binds to neuropilin-1 (NRP-1), which is recognized for its overexpression on the surface of these cells." (PMID 37266331, 2023).
glioma (continued). "We assessed the effects of Sema3A or NRP1 knockdown on glioma-forming ability in vivo." (PMID 37788099, 2023). "Preliminary data of our group suggest that Neuropilin-1 (NRP1) may be a membrane receptor that mediates the proliferation of C6 glioma cells after exogenous GDNF administration." (PMID 37594930, 2023). "Taken together, these results demonstrate that the Sema3A/NRP1 signaling axis is associated with poor prognosis, is particularly elevated in the mesenchymal subtype, and is correlated with TGF-β activity in a large glioma cohort." (PMID 37788099, 2023). "Deletion of Nrp1 from both myeloid cell types or from one of these cell populations mitigates tumor growth by slowing angiogenesis and relieving the immunosuppressive nature of the glioma TME." (PMID 36203599, 2022). "Likewise, NRP1 has been involved in glioma cell migration processes, notably in 2D and chemotaxis models." (PMID 36204684, 2022). "Interestingly, Nrp1 ablation in these murine models of glioma resulted in an increase of Nrp1-Iba1+ GAMs near the tumor border." (PMID 36203599, 2022). "The domains of Nrp1 that are engaged in these activities critically determine functional outcomes and cellular responses, especially in a tumor microenvironment as complex as that fostered by high-grade gliomas." (PMID 36203599, 2022). "SEMA3G belongs to the family of class-3 semaphorins, and studies indicate that this gene is linked to kidney diseases, suggesting important roles with neuropilin and plexin families in the etiology of cancer, and it is also an inhibitor of glioma progression by competing with VEGF for receptor NRP1." (PMID 35565241, 2022). "We utilized these compounds for in vitro assessment of SMAD2/3 following Nrp1 inhibition and activation in WT and Nrp1-KO microglial cell lines in the presence and absence of glioma associated cytokines." (PMID 36203599, 2022). "Indeed, Zhang’s team demonstrated that NRP1 mediates glioma progression through its interaction with the intracellular protein GIPC1 via the cytoplasmic C-terminal SEA motif." (PMID 34277411, 2021). "Therefore, the specific targeting property of RGE-peptide on NRP-1 was applied for active targeting in glioma." (PMID 34261493, 2021). "More importantly, NRP-1-targeted RGE-conjugated EVs have been documented to facilitate diagnosis and therapy of glioma, both in vitro and in vivo, which is in line with our finding that active targeting of ICG/PTX@RGE-EV in glioma was achieved by RGE-peptide specific targeting of NRP-1." (PMID 34261493, 2021). "NRP1 is a prognostic marker in stomach cancer, cervical cancer, renal cancer and glioma." (PMID 33521362, 2021). "Finally, we examined TCGA survival data in both low grade glioma and glioblastoma based off expression levels of these three transcripts: Sema3A, Nrp1, PlxnA1." (PMID 33302912, 2020). "Autocrine NRP1-VEGFFR signaling in gliomas may be responsible for the activation of VEGFR2, which is localized in the cytoplasm, thereby emphasizing the importance of intercellular VEGFR signaling for researchers." (PMID 30871059, 2019). "Whether NRP1 expression by GAMs drives their pro-tumorigenic phenotype and/or glioma disease progression in humans is unknown." (PMID 30479695, 2018). "Additionally, using chimeric mouse models, we have shown that NRP1 ablation from either populations of peripheral monocytes or resident microglia can repress glioma progression, suggesting discriminant functionality of these cells." (PMID 32914058, 2018). "Additionally, we highlight Neuropilin 1, a cell surface receptor protein, describe its signaling functions in the context of immunity, and point to its potential to slow glioma progression." (PMID 32914058, 2018). "RNAi knockdown of NRP1 reduced proliferation of C6 glioma cells when stimulated with GDNF." (PMID 29088765, 2017). "We observed decreased proliferation in GDNF-stimulated C6 glioma cells when NRP1 was knocked down." (PMID 29088765, 2017).
glioma (continued). "NRP1 overexpression is also reported in glioma cell lines, C6, U251 and U87." (PMID 29088765, 2017). "This suggested that NRP1 interaction with exogenous GDNF promoted proliferation of C6 glioma cells." (PMID 29088765, 2017). "NRP1 is thus a GDNF receptor in glioma cells and a potential therapeutic target." (PMID 29088765, 2017). "NRP1 mediates progression of a variety of tumors including gliomas." (PMID 29088765, 2017). "Therefore, we postulate that the recruitment of NRP1 to the C6 glioma cell membrane is necessary for effective GDNF signaling." (PMID 29088765, 2017). "The glioma cells were positively identified by neuropilin-1 (NRP-1) immunohistochemistry." (PMID 28463983, 2017). "Nrp1-deficient or EG00229-treated wild-type microglia exhibited a shift towards anti-tumorigenicity as evident by altered inflammatory marker profiles in vivo and decreased SMAD2/3 activation when conditioned in the presence of glioma-derived factors." (PMID 26755653, 2016). "Additionally, it would be critical to analyze more glioma biopsies to firmly establish a correlation of Nrp1 expression in macrophages with the severity of the disease course." (PMID 26755653, 2016). "Increased Nrp1 expression in glioma biopsies, specifically in glioma tumor cells, correlates with increased malignancy, whereas reducing Nrp1 expression in glioma cells suppresses migration, proliferation and survival in vitro, and stem cell viability and tumor growth in vivo." (PMID 26755653, 2016). "To address why Nrp1-deficient and EG00229-treated wt microglia showed differences in M1 polarization in the presence of glioma-derived mediators, we investigated whether they exhibited deficits in signaling via Nrp1-dependent pathways related to polarization." (PMID 26755653, 2016). "The RMPAhigh gliomas were enriched in immature vessel cells and tumor associated macrophages, and both cell types expressed high levels of pro-angiogenic RTKs including MET, VEGFR1, KDR, EPHB4 and NRP1." (PMID 27385209, 2016). "Neuropilin 1 (Nrp1), a cell-surface transmembrane receptor that functions as a co-receptor for several signaling pathways, has received significant attention as a potential therapeutic target in glioma as well as in other cancer subtypes." (PMID 26755653, 2016). "Previous work demonstrated a crucial role of the TMD of NRP1 and suggested that inhibition may present a therapeutic potential in glioma treatment." (PMID 27351129, 2016). "Similarly, a protumorigenic role of Sema3A was implicated by its overexpression in human GBM specimens, which acts in an autocrine fashion to promote glioma cell dispersal through neuropilin-1." (PMID 23050142, 2012). "Moreover, NRP1 overexpression was related to poor prognosis in human gliomas and with the malignancy of astrocytic tumours." (PMID 18781179, 2008). "Indeed, NRP1 expression increased significantly as glioma grade increased." (PMID 30479695, 2018). "Thus, NRP1 expression correlates with poor prognosis and tumor grade in human glioma." (PMID 30479695, 2018). "The association between NRP1 expression and patient prognosis is not well studied in glioma." (PMID 30479695, 2018). "The results of our investigation showed a strong relationship between the expression of SMARCAL1 and several immune checkpoint genes, including CD276, NRP1, TNFSF4, CD40, CD200, and CD80 in Glioma, LUAD, LIHC, KIRC, and UCEC." (PMID 39994264, 2025). "Two overexpressed receptors found on the surface of new blood vessels in gliomas are vascular endothelial growth factor 2 (VEGFR-2) and Neurolipin-1 (NRP-1)." (PMID 40002469, 2025). "NRP-1-mediated transforming growth factor-β (TGF-β) signaling promotes amplification of the anti-inflammatory genes, thereby restricting glioma-specific immunity." (PMID 41268299, 2025).
glioma (continued). "A TAT-AT7 fusion protein designed by attaching the cell-penetrating peptide TAT to a vascular-targeting peptide AT7, competitively bound to VEGFR2 and NRP-1, preventing VEGFA165 binding and targeting glioma neovascularization in vivo." (PMID 40841907, 2025). "The peptide Ft targets TN-C and neuropilin-1 (NRP-1), enhancing internalization in U87 glioma and HUVEC cells, as well as penetration in 3D glioma spheroids." (PMID 40006509, 2025). "NRP1 expression is higher in grade III astrocytomas, oligoastrocytomas, and oligodendromas compared to grade I and grade II corresponding glioma tumors." (PMID 37894289, 2023). "NRP1 expression correlates with the mesenchymal GBM subtype, a higher glioma grade, and a poorer prognosis." (PMID 37894289, 2023). "NRP1 was also shown to function as a receptor for glial-derived neurotrophic factor (GDNF) in GBM, promoting proliferation of the glioma cells." (PMID 36203599, 2022). "The RGE peptide is a specific ligand of a transmembrane glycoprotein Neuropilin-1 (NRP-1), which is overexpressed in glioma cells and the tumor vascular endothelium." (PMID 36431890, 2022). "They reported successful knockdown of VEGF and inhibition of glioma growth by loading VEGF-siRNA and docetaxel in the Angiopep-2 and neuropilin-1 targeting liposomes." (PMID 35757736, 2022). "L-A7R peptide displays a high affinity for vascular endothelial growth factor receptor 2 (VEGFR2) and neuropilin-1 (NRP-1), both of which are overexpressed on glioma and neovasculature." (PMID 34959346, 2021). "Cyclization has also been applied to longer peptides such as the heptapeptide A7R (ATWLPPR), which binds two glioma markers, VEGFR2 and NRP-1." (PMID 34959346, 2021). "NRP1 and NRP 2 are overexpressed on the surface of endothelial cells of angiogenic blood vessels and glioma cells." (PMID 34279392, 2021). "NRP1 is highly expressed in GBM, and it was confirmed in the Chinese Glioma Genome Atlas (CGGA) and GSE16011 databases that NRP1 expression is related to patient prognosis." (PMID 34843522, 2021). "In addition, a new peptide, known as the Ft peptide, could synergistically target glioma-associated TN-C and neuropilin-1 in the neovasculature, circumventing the tumor's pathologic ECM barrier, and achieving deep penetration into the glioma parenchyma for anti-GBM treatment." (PMID 33281711, 2020). "NRP1 interacts with MET and increases the ability of HGF to stimulate pancreatic carcinoma cell invasion along with the proliferation and survival of gliomas." (PMID 30871059, 2019). "In addition, NRP1-coated magnetic nanoparticles may be useful in diagnosis and therapy of gliomas." (PMID 30717262, 2019). "In U87MG glioma cells and vascular endothelial cells stimulated by hepatocyte growth factor, platelet-derived growth factor and VEGF, the intracellular domain of NRP1 induces tyrosine phosphorylation of p130Cas, which stimulates growth and invasion of gliomas." (PMID 29088765, 2017). "NRP1 was more highly expressed in human GBM brains and C6 rat glioma cells than in normal human brains or primary rat astrocytes." (PMID 29088765, 2017). "GO analysis on the list of the DEPs identified by mass spectrometry using the PANTHER Classification System showed that 3 cell adhesion molecules, NRP1, NRP2 and ATRN, were putative GDNF receptors in glioma cells with roles in biological adhesion and growth." (PMID 29088765, 2017). "In these RMPAhigh gliomas, angiogenic related RTKs including MET, VEGFR1, KDR, EPHB4, NRP1 were frequently and concomitantly expressed in CD45+ immune cells and CD105+ endothelial cells." (PMID 27385209, 2016). "TAMs are enriched in the RMPAhigh gliomas and they show high surface expression of MET, VEGFR1, KDR, EPHB4 and NRP1." (PMID 27385209, 2016). "Neuropilin-1 (NRP-1) is a membrane bound HSPG that is expressed in normal tissues and in tumors like glioma, breast, colon, and pancreas." (PMID 26558271, 2015).
glioma (continued). "Two recent studies independently demonstrated that NRP1 physically binds c-MET, and potentiates c-MET activation in response to HGF stimulation in human glioma and pancreatic cancer cells." (PMID 20085644, 2010). "In this study, we analysed mRNA expression of class-3 semaphorins, in addition to SEMA4D, VEGF, NRP1 and NRP2 expressions, in 38 adult glial tumours." (PMID 18781179, 2008). "In this study, we analysed the expressions of seven semaphorins of class-3, SEMA4D, VEGF and the NRP1 and NRP2 receptors in 38 adult glial tumours." (PMID 18781179, 2008). "We studied by quantitative real-time RT–PCR the expression of the seven semaphorins from class-3 (A-G), SEMA4D, NRP1, NRP2 and VEGF in 11 adult low-grade and 27 high-grade gliomas." (PMID 18781179, 2008). "Similarly, Roth and his team focused on NRP1 dimers, demonstrating that disrupting the dimerization motif of NRP1 weakened VEGF and Sema3A signaling, which are essential for glioma cell migration and invasion." (PMID 39685591, 2024). "Similarly, and relevant to NRP1, SEMA3A inhibited glioma-stem cell proliferation and stimulated invasion in a NRP1- and PlexinA1-dependent manner." (PMID 36203599, 2022). "Neuropilin-1 (NRP-1) is a transmembrane glycoprotein overexpressed in glioma cells and tumor vascular endothelium, but less or not expressed in normal nerve cells and other tissues." (PMID 36297672, 2022). "Specifically, EVs decorated with RGERPPR, a peptide ligand for neuropilin-1 which is highly expressed on glioma cells but not other neuronal cells, were able to target glioma cells in an orthotopic mouse model." (PMID 36591444, 2022). "Their results suggest that inhibiting VEGFR2 or NRP1 in these cells could be a safe therapy in contrast to bevacizumab, a monoclonal antibody targeting VEGF, which remains ineffective against glioma CSCs." (PMID 34277411, 2021). "For this purpose, recent literature and tumor databases were analyzed to show correlations between NRP1 and CD15 (a stem cancer cells marker), and between NRP1 and PDL1, for various pediatric brain tumors, such as high- and low-grade gliomas, medulloblastomas, and ependymomas." (PMID 34277411, 2021). "In addition, in the field of glioma-targeted therapy, researchers use click chemistry technology to couple the exosome layer with neuropilin-1-targeted peptide (RGERPPR and RGE) to form an exosome with glioma-targeting function." (PMID 34307384, 2021). "Similar to NRP2, NRP1 is expressed on various types of tumor cells and its expression correlates with tumor progression or a poorer prognosis in several cancers such as prostate, breast, non-small-cell lung carcinoma (NSCLC) and glioma." (PMID 33918816, 2021). "For example, it was reported that the functional complex of SEMA3C with its receptors NRP1/PLXNA2/PLXND1 could activate Rac1/NF-κB signaling to promote the survival and migration of glioma stem-like cells." (PMID 32640719, 2020). "The quantitative real-time PCR method was used to evaluate mRNA expression of SEMA3(A-G), neuropilins (NRP1 and NRP2), plexins (PLXNA2 and PLXND1), cadherins (CDH1 and CDH2), integrins (ITGB1, ITGB3, ITGA5, and ITGAV), VEGFA and KDR genes in 59 II-IV grade glioma tissues." (PMID 33036421, 2020). "In case of general glioma, top hub nodes included HER2 and HER4 as part of one cluster; as for astrocytoma, the top hub nodes listed CCNE2 and CDK2 as part of one cluster and VEGF and NRP1 as components of another cluster." (PMID 31952211, 2020). "Although NRP1 was not identified as an independent prognostic marker of glioma pathology, our analysis indicates that NRP1 expression in human glioma is inversely correlated with survival as well as clinicopathological features." (PMID 30479695, 2018). "Rhodocetin-αβ-induced breakdown of the tumor vessel wall barrier may be relevant also for other NRP1- and MET-expressing malignancies in which VM occurs, for example glioma/astrocytoma, prostate cancer, and gastric cancer." (PMID 29854288, 2018).